RPL22L1 (ribosomal protein L22 like 1)
Tractability: PROTAC: ubiquitination databases record sites on it; its protein half-life has been measured.
Gene: Protein-coding gene on chromosome 3 (170,864,875 to 170,870,402, reverse strand). Ensembl gene ENSG00000163584.
Subcellular location (Human Protein Atlas): Nucleoli; Nucleoli rim; Nucleoplasm
Pathways (Reactome):
Metabolism of proteins: Eukaryotic Translation Termination; Formation of a pool of free 40S subunits; GTP hydrolysis and joining of the 60S ribosomal subunit; L13a-mediated translational silencing of Ceruloplasmin expression; PELO:HBS1L and ABCE1 dissociate a ribosome on a non-stop mRNA; Peptide chain elongation; Ribosome Quality Control (RQC) complex extracts and degrades nascent peptide; SRP-dependent cotranslational protein targeting to membrane; ZNF598 and the Ribosome-associated Quality Trigger (RQT) complex dissociate a ribosome stalled on a no-go mRNA
Metabolism of RNA: Major pathway of rRNA processing in the nucleolus and cytosol; Nonsense Mediated Decay (NMD) enhanced by the Exon Junction Complex (EJC); Nonsense Mediated Decay (NMD) independent of the Exon Junction Complex (EJC)
Cellular responses to stimuli: Response of EIF2AK4 (GCN2) to amino acid deficiency
Developmental Biology: Regulation of expression of SLITs and ROBOs
Disease: Viral mRNA Translation
Metabolism: Selenocysteine synthesis
Gene Ontology:
Molecular function: protein binding; structural constituent of ribosome
Biological process: cytoplasmic translation; translation
Cellular component: cytoplasm; ribosome
Genetic constraint (gnomAD): Loss-of-function variants: 9 observed, 8.05 expected, observed/expected ratio (o/e) 1.12, 90% interval 0.67 to 1.8. That is too few expected variants to judge how well the gene tolerates losing a copy. Missense variants: 73 observed, 80.58 expected, observed/expected ratio (o/e) 0.91, 90% interval 0.75 to 1.1. Synonymous variants: 31 observed, 28.23 expected, observed/expected ratio (o/e) 1.1, 90% interval 0.82 to 1.48.
Homologues: Orthologues: macaque RPL22L1 (98% identical), mouse Rpl22l1 (96% identical), rat Rpl22l3 (84% identical), tropical clawed frog rpl22l1 (79% identical), zebrafish rpl22l1 (75% identical). Paralogues in human: RPL22 (73% identical).
Diseases named in the same sentence as RPL22L1 in open-access papers:
RPL22L1 is named in the same sentence as 31 diseases in open-access papers, as found by Europe PMC text mining. Sharing a sentence is not in itself a finding about the gene and the disease. The quoted sentences say what the papers report.
hepatocellular carcinoma (7 papers, 2022 to 2025). A malignant tumor that arises from hepatocytes. "Several studies showed that RPL22L1 is involved in the regulation of cellular functions, including cell proliferation, migration, invasion and apoptosis, and is associated with ovarian cancer, colorectal cancer and hepatocellular carcinoma." (PMID 36625246, 2023). "Although RPL22L1 expression is induced in a compensatory manner in Rpl22−/− mice and can support translation, RPL22L1 plays a pivotal role in the malignancy of colorectal cancer, hepatocellular carcinoma, and prostate cancer." (PMID 40617352, 2025). "Similarly, in hepatocellular carcinoma (HCC), RPL22L1 expression associates with malignancy and drug resistance, with potential mitigation via ERK pathway inhibition." (PMID 39045153, 2024). "RPL22L1, a component of the 60S subunit regulated by RPL22, has been found to be significantly upregulated in glioblastoma (GBM) and hepatocellular carcinoma (HCC), leading to a poorer outcome for patients." (PMID 39207452, 2024). "Besides, our team previously found that RPL22L1 activated ERK pathway independently of MAPK, promoting hepatocellular carcinoma (HCC) malignancy." (PMID 37985768, 2023).
glioblastoma (5 papers, 2023 to 2025). The most malignant astrocytic tumor (WHO grade IV). "RPL22L1 promotes resistance to temozolomide in glioblastoma by activating STT3." (PMID 39207452, 2024). "Paradoxically, the isoform of RPL22L1 that is suppressed by WIN site blockade, RPL22L1a, is linked in glioblastoma cells to ribosome function, not splicing, while the splicing-relevant RPL22L1b isoform is resistant to WINi." (PMID 38682900, 2024).
ovarian carcinoma (5 papers, 2013 to 2023). A malignant neoplasm originating from the surface ovarian epithelium. "RPL22L1, a ribosomal protein, is overexpressed in ovarian cancer and promotes cancer cell metastasis via the epithelial-to-mesenchymal transition." (PMID 35909892, 2022). "RPL22L1 can promote ovarian cancer metastasis by inhibiting vimentin and N-cadherin expression, thereby inducing epithelial-mesenchymal transition." (PMID 35513791, 2022). "RPL22L1 is critical in maintaining an aggressive phenotype in ovarian cancer and in triggering cell metastasis by inducing epithelial-to-mesenchymal transition (EMT)." (PMID 33229623, 2020).
prostate carcinoma (5 papers, 2022 to 2025). A carcinoma that arises from epithelial cells of the prostate gland. "In addition, studies have shown that RPL22L1 was elevated in human prostate cancer tissues and promoted the proliferation and invasion of prostate cancer cells." (PMID 37985768, 2023). "In addition, RPL22L1 could be used as a prognostic marker for prostate cancer and colorectal cancer." (PMID 35513791, 2022). "Furthermore, a significant upregulation of RPL22L1 and RPS21 expression in prostate cancer tissues was observed, suggesting their potential utility as diagnostic markers for prostate cancer." (PMID 39684863, 2024). "Similarly, RPL22L1 has the capability to activate the PI3K/Akt/mTOR pathway, promoting the proliferation of prostate cancer cells, offering a promising avenue for prostate cancer therapy." (PMID 39684863, 2024).
colorectal cancer (4 papers, 2019 to 2025). A primary or metastatic malignant neoplasm that affects the colon or rectum. "IHC analysis was performed on multi-tumor TMAs, which revealed that RPL22L1 is highly expressed in a variety of solid tumors including renal cell carcinoma, breast cancer, lung cancer as well as colon sarcoma and colorectal carcinoma." (PMID 31581233, 2019). "Our data reveal a link between poor colorectal cancer prognosis and RPL22L1 overexpression." (PMID 31581233, 2019).
colon cancer (2 papers, 2019). "To further explore the extent of RPL22L1 induction in human colon cancer patients and assess its relationship to outcomes, we performed RPL22L1 immunohistochemistry (IHC) on a multi-tumor and colon cancer tissue microarrays (TMA)." (PMID 31581233, 2019). "Likewise, shRNA knockdown of RPL22L1 decreased proliferation of colon cancer lines HCT116 and HT29, and the anchorage-independent cell growth of SW620, HT29 and HCT116." (PMID 31581233, 2019). "Interestingly, ectopic expression of RPL22 in HCT116 human colon cancer cells, which express higher levels of RPL22L1 than normal colon epithelial cells, repressed RPL22L1 expression." (PMID 31581233, 2019). "RPL22L1 gene was previously identified as MSI specific in gastric cancer and identified as colon cancer CIMP-H subtype (characterised as enrichment for MSI, right side and mucinous histology) specific gene." (PMID 31008109, 2019). "To further determine if RPL22L1 induction was sufficient to promote these behaviors in colon cancer cell lines, we overexpressed RPL22L1 in colon cancer cell line SW480 and found that Rpl22L1 induction was sufficient to promote growth and anchorage independence." (PMID 31581233, 2019). "The effect of Rpl22L1 on anchorage independent growth is not restricted to colon cancer cell lines." (PMID 31581233, 2019).
lung adenocarcinoma (2 papers, 2024). A carcinoma that arises from the lung and is characterized by the presence of malignant glandular epithelial cells. "No studies have reported the effect of ribosomal protein L22 like 1 (RPL22L1) in lung adenocarcinoma (LUAD)." (PMID 38577587, 2024).
Arthritis (1 paper, 2024). Inflammation of a joint. "Consequently, RPL22L1 and LY96 may help regulate immune cells and contribute to the development of arthritis." (PMID 39509434, 2024).
bladder cancer (1 paper, 2021). "To further investigate whether hub genes have an impact on the prognosis of bladder cancer, we performed survival analysis of CXCL8, MDM2, TGFB2, FN1, TIMP1, and RPL22L1, and their impact on tumor stage using TCGA database." (PMID 34276798, 2021).
colon adenocarcinoma (1 paper, 2019). "The intensity of RPL22L1 staining was variable and elevated RPL22L1 staining was found to be significantly associated with colon adenocarcinoma (n = 23)." (PMID 31581233, 2019). "Indeed, RPL22L1 expression was frequently elevated in colon adenocarcinomas relative to adjacent normal and normal colon tissue, whereas RPL22 was preferentially expressed in normal colon samples." (PMID 31581233, 2019). "IHC staining for RPL22L1 in human colon adenocarcinoma patients." (PMID 31581233, 2019). "Because RPL22 was found to be deleted frequently in CRC patients, we asked whether RPL22L1 expression was also elevated in primary human colon adenocarcinoma patient samples." (PMID 31581233, 2019).
glioma (1 paper, 2023). A benign or malignant brain and spinal cord tumor that arises from glial cells (astrocytes, oligodendrocytes, ependymal cells). "Among 179 cases of glioma tissues, 115 (64.2%) cases had high expression level of RPL22L1 protein (staining intensity 2–3 levels)." (PMID 37985768, 2023).
lymph node metastasis (1 paper, 2024). "T3/T4 stage, lymph node metastasis, distant metastasis, and stage III/IV patients accounted for 14.8%, 35.2%, 6.3%, and 24.8%, respectively, in the RPL22L1 high-expression group, whereas it accounted for 10.4%, 29%, 3%, and 16%, respectively, in the low-expression group." (PMID 38577587, 2024).
neuroblastoma (1 paper, 2020). Neuroblastoma (NB) is the most common solid, extracranial childhood tumor. "We found several highly significant RBPs including RPL22L1, RNASEH2A, PTRH2, MRPL11 and AFF2, which remain uncharacterised in neuroblastoma." (PMID 32707690, 2020).
oligodendroglioma (1 paper, 2023). A well-differentiated (WHO grade II), diffusely infiltrating neuroglial tumor, typically located in the cerebral hemispheres. "GEO and TCGA RNA-seq expression datasets were used to evaluate the mRNA expression of RPL22L1, results showed it was significantly higher in GBM and oligodendroglioma tissues than that in normal brain tissues." (PMID 37985768, 2023).
osteosarcoma (1 paper, 2022). A usually aggressive malignant bone-forming mesenchymal neoplasm, predominantly affecting adolescents and young adults. "Further analysis on the differences between metastatic and non-metastatic samples revealed six intersection genes—AIM2, RPL22L1, PDPN, PKIB, GZMA, and MDM2—that related to metastasis potential of osteosarcoma and the observed gene expression differences resulted from the changes in methylation." (PMID 36072791, 2022).
Parkinson disease (1 paper, 2024). A progressive degenerative disorder of the central nervous system characterized by loss of dopamine producing neurons in the substantia nigra and the presence of Lewy bodies in the substantia nigra and locus coeruleus. "The pathways significantly associated with RPL22L1 included ribosome, spliceosome, cell cycle, oxidative phosphorylation, Parkinson’s disease, olfactory transduction, and pyrimidine metabolism." (PMID 39207452, 2024).
Sepsis (1 paper, 2025). Sepsis is defined as life-threatening organ dysfunction caused by a dysregulated host response to infection. "At the same time, GLUL and RPL22L1 were significantly upregulated in sepsis patients and correlated with poor prognosis." (PMID 41332909, 2025).
tumor (15 papers, 2019 to 2025). "Patients with elevated RPL22L1 expression in LUAD exhibit diminished immune and stromal elements in their tumor microenvironment, suggesting a potential association between heightened RPL22L1 expression and compromised immune status in LUAD patients." (PMID 39207452, 2024). "Specifically, the results indicated that tumor status and RPL22L1 expression are independent risk factors influencing the prognosis of LUAD patients." (PMID 39207452, 2024). "Here, we report our finding that the loss of Rpl22, which serves as a tumor suppressor in some hematologic malignancies, results in the induction of its paralog RPL22L1." (PMID 31581233, 2019). "In addition, high RPL22L1 expression was positively associated with poorly differentiated grade, large tumor size and high serum AFP level." (PMID 35973992, 2022). "We utilized single-cell datasets (GSE117570 and GSE150660) from the Tumor Immune Single-cell Hub (TISCH) database to analyze the expression of RPL22L1 in LUAD TME." (PMID 38577587, 2024). "Single-cell level analysis revealed that RPL22L1 was expressed not only in malignant tumor cells but also on immune cells." (PMID 38577587, 2024). "The data of xenograft tumour assay suggested that the low expression of RPL22L1 inhibited the growth and invasion of PCa cells in vivo." (PMID 36625246, 2023). "The tumour volume and weight were significantly decreased in the RPL22L1 low expression group compared to the control group (0.36 ± 0.19 vs. 0.63 ± 0.27 g, p < 0.05)." (PMID 36625246, 2023). "We performed cell function assays, orthotopic and subcutaneous xenograft tumor models to evaluate the effects and molecular mechanisms of RPL22L1 on GBM." (PMID 37985768, 2023). "Further, clinical data showed that upregulation of RPL22L1 in HCC patients was strongly correlated with tumor differentiation, tumor size and serum AFP levels." (PMID 35973992, 2022). "Antibody HPA056207 staining for RPL22L1 in normal kidney tissue was medium, whereas it was low in tumor tissue." (PMID 34420511, 2022). "CRC tumor specimens from different patients were transplanted into nude mice, which were then treated with 5-FU or vehicle control and examined for tumor growth and RPL22L1 expression." (PMID 31581233, 2019). "Tumor samples were harvested from mice and used to construct TMAs, which were stained with anti-RPL22L1." (PMID 31581233, 2019). "The PDX samples were assembled into 5-FU sensitive (Tumor inhibition >64%) and 5-FU resistant (Tumor inhibition <30%) groups, which revealed that RPL22L1 expression was significantly higher in the 5-FU resistant group (p<0.05)." (PMID 31581233, 2019). "Furthermore, another recent work supported the tumour suppressor role of DUSP6 in cervical cancer, demonstrating that the protein ribosomal L22-like 1 (RPL22L1) is overexpressed in this type of tumour and is capable of binding and sequestering DUSP6." (PMID 40943262, 2025). "Notably, the suppression of RPL22L1 through silencing resulted in a significant inhibition of tumor weight and volume compared to the vector group." (PMID 39207452, 2024). "Single-cell analysis suggested that RPL22L1 might have a potential function in the tumor microenvironment (TME) of LUAD." (PMID 38577587, 2024). "The investigation delves into potential regulatory networks linked to RPL22L1, including its association with tumor microenvironment (TME), tumor mutational burden (TMB)/microsatellite instability (MSI), mRNA stemness index (mRNAsi), and drug sensitivity in LUAD." (PMID 39207452, 2024). "In summary, RPL22L1 may promote tumor progression by mediating an immunosuppressive microenvironment and facilitating immune escape." (PMID 38577587, 2024). "Additionally, histopathological analysis showed that tumour cells in the RPL22L1 low expression group had a weaker ability to invade into adjacent tissues compared with the control group, indicating that RPL22L1 enhanced PCa cell invasion." (PMID 36625246, 2023).
tumor (continued). "RPL22L1 has been suggested to play an essential role in the progression of various tumours." (PMID 36625246, 2023). "We also observed RPL22L1 showed an increasing trend along with tumor grades in TCGA-LIHC cohort." (PMID 35973992, 2022). "Because no commercial antibodies against RPL22 or RPL22L1 gave reliable IHC results in patient tumor samples, we developed an anti-human RPL22L1 polyclonal antibody and verified its specificity and its function in immunoblotting, immunofluorescent staining, and immunohistochemistry." (PMID 31581233, 2019). "Compositional heterogeneity also emerges at the level of RNA processing, as alternative splicing of ribosomal protein paralogs—including RPL22 and RPL22L1—differs across tumour states and cellular phenotypes, suggesting that ribosomal diversity in GBM may arise through multiple regulatory layers." (PMID 41589302, 2025). "Knockdown of RPL22L1 has been shown to suppress the activity, proliferation, migration, and invasion of LUAD cells, induce apoptosis, and attenuate tumor growth in LUAD xenografts in mice." (PMID 39207452, 2024). "The results showed that RPL22L1 enhanced the subcutaneous tumorigenicity of GBM cells, and still showed a larger tumor volume in TMZ treatment." (PMID 37985768, 2023). "Most interestingly, the alternative splicing of eL22L1/RPL22L1 was regulated by pH, and cells in the acidic tumor core were significantly enriched in eL22L1B/RPL22L1B compared to cells in the tumor periphery." (PMID 37047306, 2023). "In normal tissues, RPL22L1, INHBA, and CAPZA1 were found to be significantly increased in CRC patients for whom experienced tumor lymphatic metastasis." (PMID 35909892, 2022). "TCGA and GEO databases were used to assess the mRNA expression level of RPL22L1, and found that was statistically higher in HCC tissues than that in non-tumor livers." (PMID 35973992, 2022). "The results indicated that, as NOL12, PABPC1L, RNASE2, RPL22L1, and OASL expression increased, tumor grade, AJCC stage, T stage, and M stage in KIRC patients increased." (PMID 33229623, 2020). "NOL12, PABPC1L, RNASE2, RPL22L1, OASL, and YBX3 expression were significantly positively correlated with tumor grade and AJCC stage, while RBM47 expression was negatively correlated with tumor grade and AJCC stage." (PMID 33229623, 2020).